CRP (C-reactive protein)
Diseases named in the same sentence as CRP in open-access papers (continued):
Sharing a sentence is not in itself a finding about the gene and the disease.
colorectal cancer (continued). "We selected the level of CRP as a biomarker to measure the effect size of TNF inhibition on the risk of colorectal cancer, instead of the level of TNFR1, based on previously published literature." (PMID 36618924, 2022). "By using these cis-variants as proxies for TNF inhibition, we finally found that TNF inhibition was associated with a 2.1% absolute risk reduction in colorectal cancer per 1 mg/L decrease in CRP." (PMID 36618924, 2022). "In colorectal cancer, preoperative elevated CRP is a well-known risk factor for recurrence and has poor prognostic value cancers." (PMID 36235624, 2022). "Studies have evaluated the association between circulating CRP levels and colorectal cancer in various populations." (PMID 34361836, 2021). "In patients with colorectal cancer, increased serum CRP concentrations have been linked to poorer survival." (PMID 34572955, 2021). "Goyal and colleagues found a similar association between CRP levels and specifically in colorectal cancer mortality." (PMID 33243216, 2020). "High CRP levels have been known to be associated with poor prognosis in patients with various malignancies, such as esophageal cancer, colorectal cancer, pancreatic cancer and renal cell carcinoma." (PMID 33351844, 2020). "In colorectal cancer, CRP levels are significantly positively associated with VEGF-A (r = 0.23, p < 0.0001) and Ang2 (r = 0.43, p < 0.001)." (PMID 32002126, 2020). "The association between inflammation markers (NLR, PLR, CRP) and cancer has already been observed in various types of gastrointestinal malignancies, including esophageal cancer, gastric cancer, colorectal cancer, and pancreatic cancer." (PMID 32214401, 2020). "Previous studies indicated that a high CRP/Alb ratio was associated with large tumor size, tumor depth, microvascular invasion, and lymph node metastasis in gastric cancer, colorectal cancer, and hepatocellular carcinoma." (PMID 32856868, 2020). "Further markers of chronic inflammation, e.g., elevated CRP levels, were associated with shorter OS as described in several entities, like colorectal cancer, urothelial cancer, and lymphomas." (PMID 31717722, 2019). "Numerous studies have identified postoperative CRP concentration as a risk factor for postoperative complications after gastrointestinal cancer surgery, including colorectal cancer, esophageal cancer, and gastric cancer." (PMID 31429742, 2019). "Higher CRP levels were associated with an increased risk of colorectal cancer (OR (95% CI) = 3.58 (2.65–4.82), for the highest quartile vs. lowest quartile)." (PMID 29874787, 2018). "Both preoperative cardiopulmonary exercise test (CPET)-derived measures of fitness and postoperative C-reactive protein (CRP) concentrations are associated with complications following surgery for colorectal cancer." (PMID 29983927, 2018). "Accordingly, a high score for the CRP-dietary pattern was significantly associated with an increased risk of colorectal cancer." (PMID 29874787, 2018). "The magnitude of the postoperative systemic inflammatory response, as evidenced by CRP, is increasingly understood to be associated with the development of postoperative complications following surgery for colorectal cancer." (PMID 29983927, 2018). "In the present study, we found a strong significant association between the CRP-dietary pattern and the risk of colorectal cancer." (PMID 29874787, 2018). "Our results showed that there is strong association between MMP-9 and CRP serum levels and progression of colorectal cancer." (PMID 30154846, 2018). "The change in the level of acute-phase reactants, such as CRP, ferritin, fibrinogen, D-dimer, haptoglobin, and albumin, was found to be associated with a dismal prognosis and survival outcome in colorectal cancer patients in various settings of the disease." (PMID 29949857, 2018). "The association between the CRP-dietary pattern scores and colorectal cancer risk was examined according to the IL-17F rs763780 genotype." (PMID 29874787, 2018).
colorectal cancer (continued). "In the present study, a high CRP-dietary pattern score corresponded with a high CRP concentration, which was reported to be associated with an increased risk of colorectal cancer." (PMID 29874787, 2018). "High CRP levels were associated with a high risk of colorectal cancer (OR (95% CI) = 3.58 (2.65–4.82) for the highest quartile vs. lowest quartile)." (PMID 29874787, 2018). "The relationship between C-reactive protein (CRP) gene rs1205 polymorphism and the risk of colorectal cancer (CRC) has been investigated previously." (PMID 28706007, 2017). "During the past decade, elevated serum CRP has been associated with poorer prognosis in patients with various malignant cancers, including gastric cancer, colorectal cancer, breast cancer, and urological cancer." (PMID 27733196, 2016). "CRP gene polymorphism has been associated with increased cancer risk and worse prognosis, mainly in colorectal cancer." (PMID 26717416, 2015). "This is supported by two recent studies suggesting different risk of colorectal cancer conferred by CRP polymorphisms." (PMID 26284119, 2015). "A subsequent study by Zhang and colleagues was performed within the Women’s Health Study, which recruited female health professionals, and found an almost statistically significant inverse association between CRP and colorectal cancer." (PMID 26321888, 2015). "Several studies have demonstrated that elevated CRP levels are associated with an increased risk of early recurrence and poor outcome following colorectal cancer resection." (PMID 23833661, 2013). "Interleukin-6 (IL-6) has been used for the diagnosis of colorectal cancer and CRP was directly associated with survival/prognosis, but has been less widely used and not yet used serially." (PMID 19948067, 2009). "Increased size of the primary tumour has been linked with elevated serum CRP concentrations in patients with operable colorectal cancer, suggesting an association between tumour bulk and the magnitude of the systemic inflammatory response." (PMID 19127266, 2009). "METHODS: We conducted a nested case-control study in the JACC Study, investigating the relationship between the risk for colorectal cancer and serum levels of CRP determined by a high-sensitivity CRP enzyme immunoassay." (PMID 16127232, 2005). "Further studies, in which a distinction is made between incident cases of colorectal cancer and death from colorectal cancer, are needed to clarify the relationship between high serum CRP levels and the risk for colorectal cancer." (PMID 16127232, 2005). "In the present study, a poor tumour CD4+ T-lymphocyte infiltrate was associated with an elevated circulating C-reactive protein concentration in patients undergoing potentially curative resection for colorectal cancer." (PMID 15700032, 2005). "Odds ratio (OR) and 95% confidence interval (CI) for colorectal cancer risk by serum C-reactive protein (CRP) level for the nested case-control study in the JACC Study." (PMID 16127232, 2005). "Several studies have shown that elevated circulating C-reactive protein concentrations are associated with poor survival in patients with colorectal cancer." (PMID 15150596, 2004). "CRP was positively associated with tumor budding among male patients, while IL‐8 and sVCAM‐1 were positively associated with tumor budding among patients with early‐onset colorectal cancer." (PMID 40985344, 2025). "C-reactive protein, a frequently used acute-phase reactant in the postoperative monitoring of patients undergoing colorectal cancer surgery, can be used in the prediction of long-term survival, as elevated CRP levels in the postoperative course are associated with overall decreased survival rates." (PMID 40383853, 2025). "Elevated C-reactive protein (CRP) levels are associated with an increased risk for colorectal cancer (CRC), as well as a poor prognosis, but it remains unclear whether these associations are causal." (PMID 36996866, 2023).
colorectal cancer (continued). "Higher concentrations of the inflammatory biomarker C-reactive protein (CRP) have been associated with a moderately higher risk of colorectal cancer (CRC) in a meta-analysis of eighteen prospective studies, although significant heterogeneity was observed across individual studies." (PMID 35739525, 2022). "The role of elevated pre-diagnostic C-reactive protein (CRP) concentrations on mortality in individuals with colorectal cancer (CRC) remains unclear." (PMID 35739525, 2022). "Regarding serum CRP levels, some previous studies reported that preoperative CRP elevation was significantly associated with a poor prognosis of patients with gastric cancer, colorectal cancer, and iCCA." (PMID 33507925, 2021). "CRP has been correlated with an accumulation of myeloid derived cells with suppressor functions, which are linked to several pathologies, and a heightened risk of cancer mortality, particularly in colorectal cancer." (PMID 33243216, 2020). "Data from the Danish general population cohort of cancer free individuals followed up for up to 16 years showed that elevated levels of CRP at baseline were associated with increased risk of cancer of any type and with some specific cancers such as lung cancer and possibly colorectal cancer." (PMID 33291857, 2020). "In addition, two studies using Mendelian randomization approaches to assess the influence of inherited increases in CRP level on the risk for colorectal cancer, supported a causal relationship between increased CRP and cancer." (PMID 31622379, 2019). "Furthermore, association of chronic inflammation, seen in elevated CRP (c- reactive protein) levels, with shorter OS is described in several entities, like colorectal cancer, urothelial cancer, and lymphomas." (PMID 31717722, 2019). "However, several studies obtained a significant association between CRP 1846C>T polymorphism and colorectal cancer risk." (PMID 31142628, 2019). "Previous studies have demonstrated that high levels of CRP are associated with poor prognosis in many malignancies, including lung cancer, breast cancer, castration-resistant prostate cancer, gastric cancer, and colorectal cancer." (PMID 31164099, 2019). "Third, despite a significant association with overall risk of cancer and colorectal cancer was suggested in this meta-analysis, we only can infer but cannot conclude that CRP polymorphisms are susceptibility loci of other types of cancer, highlighting the necessity for further investigation." (PMID 26912098, 2016). "C-reactive protein (CRP), one of the inflammatory markers, was found its up-regulation was associated with poor prognosis in small cell lung cancer, osteosarcoma, prostate cancer and colorectal cancer." (PMID 27303917, 2016). "As for colorectal cancer, previous meta-analysis found that while C-reactive protein and interleukin-6 may be associated with risk of colorectal cancer, the few studies on tumor necrosis factor-α and risk of colorectal cancer mainly found null results." (PMID 27608842, 2016). "In addition to NLR, other markers of systemic inflammatory response, such as CRP and mGPS (CRP and albumin), have been shown to be risk factors for inferior survival in colorectal cancer." (PMID 25406793, 2014). "Moreover, rs6700896, also captured by rs6690625, presented strong association with C-reactive protein, a modest risk factor for colorectal cancer." (PMID 23593308, 2013). "Prospective studies have reported that an increase in circulating C-reactive protein (CRP) is associated with increased risk of colorectal cancer, and, in particular, it has been shown that genetic variation in the CRP gene influences risk of both colon and rectal cancer developments." (PMID 24073332, 2013). "Colorectal cancer was positively associated with serum hs-CRP level." (PMID 21368452, 2011).
colorectal cancer (continued). "Persistent elevation of CRP, using several measurements weeks or months apart, has also has been reported for the detection of the presence of colorectal cancer and independently associated with the increased risk of colorectal cancer in men, and overall cancer risk." (PMID 19948067, 2009). "Many studies have demonstrated association between CRP and colorectal cancer." (PMID 27956962, 2009). "In the present study, an elevated C-reactive protein concentration was associated with poorer survival, independent of age and Dukes stage, in patients receiving adjuvant chemotherapy following potentially curative resection for colorectal cancer." (PMID 16721360, 2006). "There is also increasing evidence that the presence of a systemic inflammatory response, as evidenced by elevated circulating concentrations of C-reactive protein, is associated with early recurrence and poorer survival in patients undergoing potentially curative resection for colorectal cancer." (PMID 15700032, 2005). "We investigated whether serum levels of C-reactive protein (CRP), a biomarker of inflammation, are associated with colorectal cancer, using serum samples collected in the Japan Collaborative Cohort Study (JACC Study)." (PMID 16127232, 2005). "In the present study, we used sera from the Japan Collaborative Cohort (JACC) Study to investigate whether high serum CRP levels are associated with the risk of colorectal cancer in Japanese." (PMID 16127232, 2005). "Furthermore, in colorectal cancer at least, there is increasing evidence that the presence of an elevated C-reactive protein concentration is associated with reduced survival." (PMID 15305191, 2004). "There is increasing evidence that the presence of a systemic inflammatory response, as evidenced by elevated circulating concentrations of C-reactive protein, is associated with increased recurrence and poor survival in patients undergoing potentially curative surgery for colorectal cancer." (PMID 15150596, 2004). "Therefore, we assumed that the CRP-dietary pattern in this study could predict the risk of colorectal cancer successfully." (PMID 29874787, 2018). "Elevated CRP levels may be associated with a worse prognosis in colorectal cancer patients." (PMID 15569387, 2004). "For individuals with low CRP levels (< 3 mg/L), LE8 was associated with decreased risks of overall, breast, and colorectal cancers." (PMID 41554683, 2026). "Few studies reported the significance of a postoperatively elevated CRP response as a marker for long-term survival in patients undergoing minimally invasive surgery for colorectal cancer." (PMID 40383853, 2025). "Postoperative CRP level is an independent predictive indicator for POD among elderly colorectal cancer patients." (PMID 40146749, 2025). "Hazard ratios and their 95% CI for incident colorectal cancer risk associated with increased BMI, WHR, WC, and CRP, including all years of follow‐up and after exclusion of the first 4 years of follow‐up." (PMID 39791283, 2025). "Compared with the usual care, physical exercise reduced C-reactive protein by a mean of −0.33 mg/dL (95% CI −0.62 to −0.04) in colorectal cancer patients." (PMID 40642165, 2025). "We emphasize that CRP-4POD levels in the subgroup of patients who underwent colorectal cancer surgery excluding those with dehiscence were also statistically significantly related to the occurrence of any type of complication." (PMID 40392334, 2025). "A systematic review concluded that there was sufficient evidence for n-3 LCPUFAs to reduce systemic CRP concentrations in patients with colorectal cancer, suggesting their potential anti-inflammatory benefits in this population." (PMID 40523478, 2025). "Elevated C-reactive protein (CRP) levels and derived indices, such as the CRP-to-albumin ratio (CAR), have been repeatedly linked to worse overall survival in colorectal cancer." (PMID 41154372, 2025).
colorectal cancer (continued). "Li Li C C C-reactive protein (CRP) as a prognostic factor for colorectal cancer after surgical resection of pulmonary metastases C-reactive protein (CRP) as a prognostic factor for colorectal cancer after surgical resection of pulmonary metastases Bull." (PMID 40664764, 2025). "The study aimed to investigate if periodontal treatment influences the blood levels of C-reactive protein (CRP) in colorectal cancer patients." (PMID 40272186, 2025). "Conversely, CRP demonstrated greater prognostic ability for lung cancer and possibly colorectal cancer, as well as ovarian cancer in women." (PMID 40188292, 2025). "According to a recent study, patients with elevated CRP levels after the first postoperative month have lower overall and colorectal cancer-specific survival rates." (PMID 39621059, 2024). "The C-reactive Protein to Albumin Ratio has been demonstrated to predict unfavorable outcomes in colorectal cancer, oral squamous cell carcinoma, gallbladder cancer, lung cancer, and thoracic esophageal cancer." (PMID 38500655, 2024). "Studies that have shown certain links between blood CRP levels and specific cancer types—most frequently lung, breast, and colorectal cancer—can be found in the literature, generally with higher levels of CRP being associated with worse prognosis." (PMID 39335753, 2024). "In patients with colorectal cancer, authors reported increasing trends of IL-6 and CRP across stratified levels of deficit accumulation frailty (geriatric assessment domains) ranging from fit to frail." (PMID 37213604, 2023). "CRP is a robust and well-described marker in elective colorectal cancer resection, but a retrospective study has shown the limited predictive power of CRP in patients undergoing major liver resection." (PMID 37747507, 2023). "In colorectal cancer, an inverse relationship was found between the systemic inflammatory response (elevated CRP with cut-off 10 mg/L) and FoxP3+ Tregs infiltration in the intratumor stroma." (PMID 36980787, 2023). "The most obvious laboratory indicator in patients with colorectal cancer and retroperitoneal abscess is an increase in inflammation related indicators, including white blood cells, CRP, and procalcitonin." (PMID 37941542, 2023). "On the other hand, only a few articles use CAR to predict AL following colorectal cancer surgery, and only one article used the trajectory model of CRP to predict AL." (PMID 37601530, 2023). "For CRP, previous prospective studies have shown increased risks of colorectal cancer, and of lung cancer among ever smokers, in association with higher blood levels." (PMID 34935094, 2022). "A few studies have revealed a relationship between CRP-related parameters and survival in patients with colorectal cancer." (PMID 36229569, 2022). "As shown in previous prospective studies, WBC and CRP levels were increased on POD1 of colorectal ESD or laparoscopy-assisted colectomy for colorectal cancer." (PMID 35454920, 2022). "Among laboratory tests required, a full blood count to exclude colorectal cancer, C-reactive protein to exclude inflammatory bowel diseases, and serological screening for coeliac disease should be performed." (PMID 38045643, 2022). "The Sparreboom's prediction model was first validated, which showed that for patients with colorectal cancer, serum CRP, and peritoneal MMP9 is also reliable for diagnosing AL on POD3." (PMID 35657137, 2022). "The instrument of TNF-inhibition was associated with a significantly lower risk of colorectal cancer, and the results showed an absolute risk reduction of 2.1% (the IVW analysis, 95%CI 0.4%–3.8%, p = 0.012) per 1 mg/L reduction in CRP." (PMID 36618924, 2022). "Consistent with our findings, histidine level was negatively related to indicators of systemic inflammation, such as NLR, IL-6, and CRP, in patients with colorectal cancer." (PMID 35371012, 2022).